INS (insulin)
Diseases named in the same sentence as INS in open-access papers (continued):
Sharing a sentence is not in itself a finding about the gene and the disease.
diabetes (continued). "One patient developed grade 3 late hematuria and bladder tamponade; however, this complication may have partially been affected by anticoagulant and antiplatelet use accompanied by diabetes mellitus requiring insulin injection." (PMID 38778824, 2024). "It is not surprising that diabetes is a risk factor for SARS-CoV-2 infection given the effect that proinflammatory cytokines can have on insulin signaling and glucose metabolism." (PMID 38390960, 2024). "The association between obesity and impaired serum glycemic level and progression towards diabetes is through various cellular mechanisms (alterations in insulin signaling, glucose transport and dysfunction of pancreatic β cells), enhanced oxidative stress and inflammation." (PMID 39474345, 2024). "Therefore, this article aims to reveal the potential of photoactivatable drugs in treating diabetes by targeting light-activated insulin." (PMID 38542928, 2024). "Diabetes technology, specifically continuous glucose monitoring and automated insulin delivery systems, are considered the gold standard for management of T1D, yet access to these technologies varies widely across countries and regions, and varies widely even within high-income countries." (PMID 39703363, 2024). "As previously discussed, most of the existing PoC models that currently exist focus on the characterization of the pancreatic cells involved in T1D and the insulin release from the islets in response to glucose, which is a great starting point for diabetes research." (PMID 38957150, 2024). "Moreover, GM plays an integral role in diabetes development by modulating various pathophysiological processes, including insulin secretion, insulin sensitivity, immune system regulation, and glycemic and lipid regulation." (PMID 38562415, 2024). "It is classified into type 1 (insulin-dependent) and type 2 (insulin-independent) diabetes." (PMID 39323638, 2024). "The aim of the present study was to compare the acute effects of a common snack and a plant-based snack bar (PB) that was developed at the University of Thessaly as a functional diabetic snack on blood glucose and insulin in patients with type 2 diabetes mellitus (T2DM)." (PMID 39767064, 2024). "Nearly half of patients with MIDD require insulin within 10 years of diabetes diagnosis." (PMID 39738754, 2024). "Although most cases not controlled by thiamine treatment alone were treated with insulin, further study could reveal the utility of treatment with other diabetes medications." (PMID 39025920, 2024). "The delivery of insulin through nanocarriers is of particular significance due to its ability to provide a more convenient, secure, and non-invasive approach to administering insulin, ultimately overcoming challenges such as insulin resistance in the management of diabetes." (PMID 39771551, 2024). "Intriguingly, increased plasma levels of 25-OHC and 27-OHC (preproducts of 7α,25-OHC and 7α,27-OHC) have been described in people with diabetes, and 7α,25-OH protects human islets against glucotoxicity-induced β-cell damage, as well as potentiate insulin secretion." (PMID 39545055, 2024). "Given the significance of copper ions in keeping insulin stability and the advantageous impact of the complex in decreasing carbohydrate digestion, these complexes have potential utility in the treatment of individuals with diabetes." (PMID 39459337, 2024). "In the Look AHEAD trial, any remission rates were significantly higher among people who had a shorter duration of diabetes, substantial weight loss or increased physical activity, lower HbA1c levels and did not use insulin at recruitment." (PMID 38162116, 2024). "Animal research further suggests that deficiency in hepatic vitamin D receptors, which regulate intra-hepatic lipid accumulation, or vitamin D insufficiency itself, impairs insulin secretion from pancreatic beta cells, highlighting vitamin D's beneficial role in diabetes and insulin resistance." (PMID 38509247, 2024).
diabetes (continued). "The conventional treatment approach for diabetes was characterized by the administration of one to three daily injections, typically involving greater insulin doses and resulting in poorer glycemic control compared to intensive insulin therapy and insulin pump therapy." (PMID 38397939, 2024). "Research continues into even faster-acting insulins, insulin inhalers, and new insulin delivery systems such as insulin pumps and closed-loop systems that integrate insulin delivery with continuous glucose monitoring to offer personalized, real-time diabetes management." (PMID 39734941, 2024). "However, when the pulsatile pattern of pancreatic insulin in the portal circulation is diminished or almost disappeared, as can be found in prediabetes and early diabetes, systemic (post-hepatic) insulin levels will increase." (PMID 38791525, 2024). "Moreover, it has been reported that MLT has a potential effect on diabetes and its complications via regulating insulin secretion." (PMID 38988702, 2024). "I tend to forget or skip my diabetes medication (e.g. insulin, tablets)." (PMID 39044279, 2024). "Even if the risk from immunosuppression can be eliminated, there is also the question of where cell therapy falls within the pipeline of standard of care treatments for poorly controlled diabetes, in the face of insulin therapy or insulin pumps which are less invasive." (PMID 38650946, 2024). "Patients at higher risk of perioperative hypoglycemia, in particular, include those with type 1 diabetes, longer duration of diabetes, history of hypoglycemia, poor nutritional status, low body mass index (BMI), and patients who use insulin, sulfonylureas, or a meglitinide." (PMID 39458209, 2024). "Once the level of NAD + decreases, it may interfere with the metabolic activity of these cells, resulting in a reduction of insulin production, which in turn increases the possibility of diabetes." (PMID 39411062, 2024). "In recent years, studies have also confirmed that curcumin can prevent multiple diabetes complications by improving glucose and lipid metabolism, increasing insulin sensitivity, reducing insulin resistance, and ameliorating oxidative stress and inflammatory pathway status in both diabetes and DR." (PMID 39500360, 2024). "However, in patients with diabetes, the system is constantly challenged by two primary factors: defective insulin secretion by pancreatic β cells and the incapacity of insulin‐sensitive tissues to respond to insulin." (PMID 38664885, 2024). "Diabetes mellitus (DM) is a complex and heterogeneous disease classified as a group of metabolic disorders characterized by chronic hyperglycemia resulting from defects in insulin secretion, insulin action, or both." (PMID 39598447, 2024). "Diabetes is a heterogeneous medical condition marked by high blood sugar (glucose) levels or hyperglycemia due to impairment of insulin secretion or defects in the action of insulin or a combination of both factors." (PMID 38431569, 2024). "In school settings, policy implications to tackle pediatric diabetes, including coordinated post-discharge care using telemedicine, educating patients, families, and school staff about blood glucose monitoring, insulin dosage modulation, and related sick day supplies, were outlined." (PMID 39310630, 2024). "A qualitative study concluded that women with T1DM were negatively influenced by additional factors associated with DM regarding their sexual function, including visible tissue damage due to insulin injection, fear of hypoglycemia during sexual contact, and wearable diabetes technologies." (PMID 38353886, 2024). "Factors contributing to poor glycemic control in children with T1DM include insulin dose determination and administration as well as factors such as being separated from their mothers, being over 1 year old, having diabetes for more than 5 years, and having elevated serum triglyceride levels." (PMID 39895840, 2024).
diabetes (continued). "However, a notable portion of people with diabetes mellitus (DM) show suboptimal insulin injection technique practices." (PMID 38304656, 2024). "Type 2 diabetes mellitus (T2DM) is a persistent metabolic condition associated with increasing concentrations of glucose in the blood characterized by impaired insulin action and/or inadequate insulin secretion." (PMID 38323108, 2024). "In subjects with diabetes, SGLT2is improve glucose control through various mechanisms including an improvement of insulin sensitivity and secretion, improvement hepatic insulin sensitivity, and enhancement of pancreatic β-cell function through protection of cells from glucose toxicity." (PMID 39342254, 2024). "Individuals with diabetes are a heterogenous population, with the approaches used for glycaemic management varying from diet and lifestyle modification to oral medications and subcutaneous insulin." (PMID 39358593, 2024). "Additionally, a significant reduction in the HOMA-IR index was observed in the POW and PO groups, indicating an improvement in insulin sensitivity and better glucose management, crucial aspects in preventing type 2 diabetes mellitus and metabolic syndrome." (PMID 38732523, 2024). "Thiazolidinediones are another group of insulin sensitizers that could treat diabetes mellitus and obesity." (PMID 39201722, 2024). "In addition, the application of GLP-1 agonists can also reduce the daily insulin dosage of patients with diabetes and HD, and reduce the occurrence of hypoglycemia." (PMID 39628691, 2024). "Six (13%) systems supported medical and prescribing decisions such as whether and how to change insulin doses in patients with diabetes." (PMID 39296586, 2024). "Insulin therapy for diabetes did not associate with the outcomes (p > 0.05 for anatomical and functional comparisons)." (PMID 39636335, 2024). "Thus, it is known that detectable insulin concentrations are still present in some people with long-standing diabetes, as autoimmune destruction of human β-cells in T1DM patients is not always complete." (PMID 39045459, 2024). "Additionally, the duration of diabetes, education level, and insulin treatment were identified as predictors of FOH." (PMID 38378559, 2024). "Furthermore, MIDY pigs provide an interesting model for testing if diabetes treatments, e.g. insulin replacement therapies or SGLT2 (also known as SLC5A2) inhibitors, can revert the observed pulmonary alterations." (PMID 38900131, 2024). "Furthermore, fenugreek seed contains an unusual amino acid called hydroxy isoleucine, which increases insulin secretion and helps to prevent diabetes." (PMID 38371502, 2024). "Saxagliptin, a competitive inhibitor of dipeptidyl peptidase-4 (DPP-4), stands as a cornerstone in diabetes management, enhancing insulin production by elevating glucagon-like peptide-1 (GLP-1) levels and promoting the conversion of GLP-1 into its inactive form." (PMID 38399334, 2024). "Impaired insulin signaling in diabetes may be one of the primary factors that contribute towards PNS dysfunction and neuropathic symptoms." (PMID 39061964, 2024). "For instance, patients with diabetes may be treated with insulin or other hypoglycemic agents, which could alter inflammatory responses and coagulation statuses, thereby indirectly modifying the action of aspirin." (PMID 39346559, 2024). "Eventually 27% of patientswith diabetes become insulin-dependent." (PMID 39090166, 2024). "In addition, individuals with pre-diabetes showed a reduction in appetite and an improvement in tissue sensitivity to insulin, blood pressure, and oxidative stress." (PMID 39519533, 2024). "Treated diabetes patients may have lower insulin levels particularly patients on insulin sensitizers like metformin and thiazolidinediones." (PMID 38664791, 2024).
diabetes (continued). "Diabetes mellitus (DM) is a chronic metabolic disorder characterized by chronic hyperglycemia due to disturbances of carbohydrate metabolism resulting from defects in insulin secretion, insulin action, or both." (PMID 39767085, 2024). "However, a diagnosis of diabetes was a strong predictor, of returning to IV insulin infusion (OR = 10.389) [χ2 = 23.352, p < 0.001]." (PMID 39590191, 2024). "It is proposed that targeted combinations of AAs that maximise insulin secretion and mitigate (fasting) hyperglucagonaemia, could be considered for clinical applications in patients with diabetes." (PMID 39114126, 2024). "Davis incorporated a polyacrylamide (PAA) hydrogel loaded with insulin for patients combatting diabetes and discovered that protein diffusivity was inversely proportional to the molecular weight, which was inversely logarithmically dependent on the polymer concentration." (PMID 38675344, 2024). "However, important components of self-care include following a healthy diet, regular physical activity, monitoring blood glucose, adherence to insulin therapy, and having healthy coping and problem-solving skills related to diabetes self-management." (PMID 38442115, 2024). "However, the discovery of insulin in the 1920s enabled people with diabetes to countervail hyperglycemia despite high-carbohydrate diets." (PMID 39796465, 2024). "Moreover, OAB participants had higher levels of diabetes-related markers, including glycohemoglobin, fasting glucose, and insulin." (PMID 38745959, 2024). "Moreover, substantial literature shows that activity supports diabetes management by enhancing beta-cell function, improving insulin sensitivity, and reducing inflammation." (PMID 39796544, 2024). "Evidence of a low diet quality and eating frequency among insulin takers may help to inform and justify nutrition education to control and manage diabetes and to tailor consumer education." (PMID 39458437, 2024). "The multivariable-adjusted (sex, age, APACHE II score, mechanical ventilation, creatinine, diabetes, use of glucocorticoid, and use of insulin) hazard ratios (HRs) for 30-day mortality across ascending tertiles of CGI were 1.00, 0.68 (95% CI 0.38–1.22) and 0.36 (95% CI 0.19–0.70), respectively." (PMID 38762634, 2024). "The risk of LEA decreased with regular exercise (HR, 0.673; 95% CI, 0.623–0.726) after adjusting for other variables like age, sex, smoking status, alcohol consumption, income status, BMI (kg/m2), hypertension, dyslipidemia, diabetes duration, insulin, and ≥3 oral hypoglycemic agents." (PMID 39435756, 2024). "(iv) It shows post-feeding glycemic kinetics comparable to those of a healthy group, suggesting that this approach may offer greater therapeutic potential for diabetes than long-acting or fast-acting insulin." (PMID 39279997, 2024). "As a result, learning more about iron overload status in people with diabetes may provide light on oxidative stress, insulin resistance, and the likelihood of developing diabetic vascular problems." (PMID 38420099, 2024). "Although insulin and glucagon are also able to act as counter-regulatory hormones following hypoglycemia, it is mostly the adrenaline-driven mechanisms that restore normal glucose levels during hypoglycemic events in patients with diabetes." (PMID 39375537, 2024). "Indeed, supplementing a moderate carbohydrate diet with psyllium, even for a short duration, appears to be capable of significantly reducing fasting plasma insulin in those living with diabetes." (PMID 38844885, 2024). "Thus, IDE regulates processing of the key T1D autoantigen insulin in beta cells and thereby diabetes pathogenesis." (PMID 39600694, 2024). "The percentage of insulin-positive cells (beta cell area) for each islet was also quantified in the pancreas sections stained for insulin from vaccinated mice with progressive and compared with the acute onset of diabetes." (PMID 38781241, 2024).
diabetes (continued). "We tried to compare the efficacy and safety of once-weekly versus once-daily insulin in individuals with different types of diabetes or whether they had been treated with insulin in the past." (PMID 39629047, 2024). "Testosterone enhances insulin sensitivity although this does not translate into a reduced risk of developing diabetes or improved glycaemic control in men with diabetes." (PMID 39370498, 2024). "However, as the duration of diabetes increases, the proportion of persons receiving combination therapy with insulin or insulin alone increases, while the proportion of other types of treatment decreases." (PMID 39081469, 2024). "Of the 2283 patients in the diabetes group, 715 (31.3%) required treatment with insulin." (PMID 38769562, 2024). "The purpose of this study is to establish a diabetes mellitus (DM) model in Sprague Dawley (SD) rats using alloxan evaluated by assessing alloxan dosage, the induction rate of diabetes, and glucose stability through insulin treatment." (PMID 39070316, 2024). "Nonetheless, our study provides important data to suggest that interventions of diabetes control should focus on at-risk groups for diabetes-related blindness including those on insulin, those with longer diabetes duration, and those with lower education levels." (PMID 39587498, 2024). "Differences in diabetes remission and insulin levels from various bariatric procedures may explain variations in cancer risk." (PMID 39594685, 2024). "However, when co-administered with NA, STZ’s toxic effects on pancreatic β cells can be mitigated, preserving a certain number of β cell activities and resulting in insulin secretion impairment characteristic of diabetes." (PMID 39728311, 2024). "Diabetes mellitus (DM) is a metabolic disorder characterized by chronic hyperglycemia and disorders in the metabolism of carbohydrates, fats, and proteins due to defects in the secretion and/or action of insulin." (PMID 38392580, 2024). "Additionally, 44.5% of participants were using insulin injections as monotherapy for their diabetes." (PMID 38586730, 2024). "Insulin, metformin, and sulfonylureas are the first-line drugs for diabetes therapy." (PMID 38255878, 2024). "Recent studies have found that the development of a hybrid closed-loop system reduces the burden of diabetes management in patients with T1D, enables glucose-responsive insulin delivery, and protects against hypoglycemia, resulting in improved glycemic control." (PMID 39450111, 2024). "Impairment of insulin signaling and post-receptor intracellular mechanisms in insulin resistance is manifested by reduced glucose transport to myocytes and adipocytes, and its improvement is one of the main pharmacotherapeutic mechanisms in diabetes treatment." (PMID 38399444, 2024). "Thus, the present study displays the most recent data about the risks and benefits of gliflozins in patients with Type 1 Diabetes Mellitus (T1DM) with automated insulin delivery (AID) systems." (PMID 38396657, 2024). "Diabetes was defined as current use of oral hypoglycemics, insulin, and/or HbA1c ≥6.5%." (PMID 39492946, 2024). "Therefore, decreased insulin secretion or increased insulin resistance hampers intracellular insulin signaling and contributes to the development of diabetes, either type 1 diabetes (T1D) or type 2 diabetes (T2D), respectively." (PMID 38212312, 2024). "In addition, participants in Chennai had a longer duration of diabetes, were on insulin treatment, and had lower total KAP scores, all of which are known to be associated with increased risk of STDR." (PMID 38167028, 2024). "The aim of the current study was to investigate mechanisms by which betaine might reduce (i.e., improve) hepatic insulin resistance in vivo in an animal model of diabetes and fatty liver." (PMID 39119463, 2024).